RNU6-703P (RNA, U6 small nuclear 703, pseudogene)
Gene: Small nuclear RNA gene on chromosome 8 (98,048,856 to 98,048,962, forward strand). Ensembl gene ENSG00000252755.
Homologues: Orthologues: chimpanzee U6 (98% identical), rat LOC120096455 (81% identical), dog U6 (70% identical). Paralogues in human: RNU6-628P (81% identical), RNU6-242P (80% identical), RNU6-380P (80% identical), RNU6-11P (79% identical), RNU6-238P (79% identical), RNU6-37P (79% identical), RNU6-903P (79% identical), RNU6-10P (79% identical), RNU6-115P (79% identical), RNU6-116P (79% identical), RNU6-1175P (79% identical), RNU6-12P (79% identical), and 1282 more.